BCL6 (BCL6 transcription repressor)
Diseases named in the same sentence as BCL6 in open-access papers (continued):
Sharing a sentence is not in itself a finding about the gene and the disease.
B-cell lymphoma (continued). "FNAB with cell block is an equally effective alternative to core biopsy and excisional biopsy for assessment of MYC, BCL2, and BCL6 FISH, which is required for identification of the clinically aggressive subset of large B-cell lymphomas that carry both MYC and BCL2 rearrangements." (PMID 38903717, 2024). "Importantly, 5%-15% of large B-cell lymphomas bear a translocation in MYC and BCL2 or BCL6, and 20%-30% of the cases are double expressors." (PMID 37457123, 2023). "WHO-HAEM4R had introduced two categories of HGBL, namely “high-grade B-cell lymphoma with MYC and BCL2 and/or BCL6 rearrangements” and “high-grade B-cell lymphoma, not otherwise specified (NOS)”." (PMID 37190213, 2023). "B-cell lymphomas are characterized by chromosomal translocations of regions with important oncogenes and tumor suppressor genes, including C-MYC, Cyclin D1 (CCND1), B-cell lymphoma 2 (BCL2) and B-cell lymphoma 6 (BCL6)." (PMID 35740251, 2022). "Intraocular manifestations of systemic DLBCL are rare and there are no data about intraocular manifestations of high-grade B-cell lymphoma with MYc and BCL6 rearrangements." (PMID 35334633, 2022). "In B cell lymphomas, it was shown that DNA methylation might prevent CTCF-mediated silencing of the oncogene BCL6, and BCL6 transcription was upregulated." (PMID 35885590, 2022). "Only 12 cases (2.8%) were true new entities, including seven cases of high-grade B-cell lymphoma NOS, three of anaplastic large B-cell lymphoma, ALK-negative, 1 case of HHV8+ DLBCL NOS, and 1 of high-grade B-cell lymphoma with C-MYC and BCL2/BCL6 rearrangement." (PMID 35932211, 2022). "Therefore, our data suggested that AID is a poor prognostic marker of High-grade B-cell lymphoma with MYC and BCL2 and/or BCL6 rearrangements, as it has a different pathological background." (PMID 34945004, 2021). "In addition, in a subset of so called double- or triple-hit B-cell lymphomas concurrent translocations involving MYC and BCL2 and/or BCL6 occur." (PMID 34210001, 2021). "Between five and ten percent of DLBCL have concurrent rearrangements of MYC, BCL2, and/or BCL6 and are now recognized as a distinct entity in the 2016 WHO classification of lymphoid neoplasms as ‘high-grade B-cell lymphoma with MYC, BCL2, and/or BCL6 rearrangements (DHL/THL)’." (PMID 34830747, 2021). "Especially when combined with a BCL2 and/or BCL6 rearrangement (high-grade B-cell lymphoma with MYC and BCL2 and/or BCL6 rearrangement), these DLBCL have a poor outcome when treated with standard R-CHOP chemotherapy, and may require a different treatment." (PMID 32979109, 2021). "The prognostic implications of DHL and THL underlie the 2017 World Health Organization (WHO) update, which includes the cytogenetically defined category of “High grade B cell lymphoma with MYC and BCL2 and/or BCL6 rearrangements” (DHL/THL) as its own distinct entity." (PMID 31932576, 2020). "Hence, the study aims to characterize the patterns of BCL6, BCL2 and C-MYC gene aberrations in Malaysian B-cell NHL using interphase FISH." (PMID 31892985, 2020). "Of note, with these studies, it became clear that CD79 and MYD88 mutations were mutually exclusive with other known recurrent alterations occurring in DLBCLs, such as translocations of MYC and BCL2 and/or BCL6, as observed in the new WHO category of high-grade B-cell lymphomas." (PMID 33050534, 2020). "Bcl-6, IRF-4 (MUM-1) and Bcl-2 were often detected in patients with HBsAg-positive B-cell NHL." (PMID 31120924, 2019). "In recognition of its unique biology and clinical behavior, DHL has been included in the 2016 revision of the World Health Organization (WHO) classification of lymphoid neoplasms as a new category of “high-grade B-cell lymphoma (HGBL) with MYC and BCL2 or BCL6 rearrangements”." (PMID 30323893, 2018).
B-cell lymphoma (continued). "Rearrangements of MYC, BCL2, and/or BCL6 can be demonstrated using conventional cytogenetic techniques (karyotype) and/or FISH; this is a requirement for the diagnosis of cases of high-grade B cell lymphoma with DH/TH (Grade 2A)." (PMID 30190794, 2018). "Immunohistochemical stain revealed that tumor cells were diffusely positive for CD20, CD79a, bcl-2, and negative for CD3, CD5, CD10, cyclin D1 and bcl-6, which excludes the possibility of low grade B-cell lymphoma other than EMZL." (PMID 26111022, 2015). "Aggressive B-cell lymphomas with the genetic rearrangements of MYC, BCL2 and BCL6 may show either a blastoid morphology or an intermediate morphology between Burkitt lymphoma (BL) and DLBCL or, in half of cases, may be morphologically indistinguishable from DLBCL, NOS." (PMID 39684922, 2024). "Previous studies have demonstrated that HBV infection of B cell lymphomas can alter B-cell-specific signaling pathways by enhancing overall gene mutations, including CD70, or by increasing non-silent mutations or gene translocations, such as BCL6." (PMID 39532842, 2024). "Therefore, impacting the function of BCL6 via HOXB5 or miR10a as shown here, may well be of tumorigenic relevance, both in SC-1 cells and more generally in B-cell lymphoma." (PMID 37371852, 2023). "In mice, overexpression of Peli1 stabilizes Bcl6 resulting in B cell lymphomagenesis, and in diffuse large B cell lymphoma (DLBCL) patients, poor prognosis is followed by a higher level of Peli1 and Bcl6, indicating that Peli1 is a novel oncogenic signal in B cell lymphoma." (PMID 37176148, 2023). "Furthermore, BCL6 interactions with co-repressor proteins BCOR and NCOR1/2, which were differentially expressed in our dataset, represent another key regulator of GC B cell function that is dysregulated in B cell lymphomas." (PMID 36619973, 2023). "High-grade B-cell lymphoma (HGBL) with MYC and Bcl-2 and/or Bcl-6 rearrangements is an aggressive mature B-cell lymphoma that harbours a MYC rearrangement at chromosome 8q24 and a rearrangement in Bcl-2 (at chromosome 18q21) and/or in Bcl-6(at chromosome 3q27)." (PMID 36618391, 2022). "A biopsy of the right mammary gland tumor was performed, showing CD20 (+), CD21 (-), bcl-2 (+), CD10 (+), CD30(-), bcl-6 (+), MUM-1 (+), C-myc (70%+), CD19 (+), TDT (-), MPO (-), Ki-67 (+90%), MYC, and BLC2 rearrangements; a pathological diagnosis of high-grade, double-hit B-cell lymphoma was made." (PMID 36032118, 2022). "Special emphasis was laid on this group of aggressive B-cell lymphomas in recognition of its complicated classification due to the concurrence of features of both Burkitt lymphoma (BL) and diffuse large B-cell lymphoma (DLBCL) including cytogenetic aberrations affecting MYC, BCL2 and/or BCL6." (PMID 33672644, 2021). "The poor outcome of high-grade B-cell lymphoma, with rearrangements of MYC, BCL2 and/or BCL6, also known as double-hit lymphoma or triple-hit lymphoma (DHL or THL), has been well documented, while the clinical significance of extra copies of MYC, BCL2 or BCL6 are still less well known." (PMID 31315646, 2019). "However, the negative TdT and expression of BCL6 in a subset of malignant cells raise the possibility of a high grade B-cell lymphoma with MYC and BCL2 rearrangements or a lymphoblastic transformation of follicular lymphoma, although there is no clinical evidence to support these diagnoses." (PMID 38175445, 2023). "Thus, if interaction with BCL6 enables nuclear translocation of LITAF, which subsequently represses BCL6 expression, this could explain the observed differences in subcellular localization between the two reports on B-cell lymphoma." (PMID 27764808, 2016). "Considering that mutations in 5' noncoding sequences of BCL6 were frequent in B-cell lymphoma, which might contain potential regulatory regions, three pairs of primers were designed to amplify enrichment sites with specific binding motif (CTCCC) around the first exon of BCL6, respectively." (PMID 27764808, 2016).
B-cell lymphoma (continued). "FISH analysis of a large B-cell lymphoma revealed an atypical MYC rearrangement with amplification (ampR1-3G), an atypical BCL6 rearrangement (1-3R2-3F signal pattern), and no IGH::MYC fusion." (PMID 41010038, 2025). "The immunophenotypic profile-predominance of CD20+ and PAX 5+ B cells with BCL6 expression and BCL2 negativity is characteristic of reactive nodal or cutaneous lymphoid hyperplasia, as opposed to most B-cell lymphomas." (PMID 40559769, 2025). "Three (4%) patients harbored MYC and BCL6 rearrangements, while none exhibited high-grade B-cell lymphoma with MYC and BCL2 and/or BCL6 rearrangements." (PMID 40715072, 2025). "In our case, image-guided core biopsy demonstrated a CD20-positive, MYC-rearranged B-cell lymphoma with a nearly 100% Ki-67 proliferation index and no BCL2 or BCL6 rearrangements." (PMID 41362384, 2025). "Loss of expression of pan B‐cell antigens, such as CD20, has been used to argue for a diagnosis of B‐ALL/LBL, while the expression of mature B‐cell antigens such as BCL6 and MUM1 favours the diagnosis of mature rather than precursor B‐cell lymphoma." (PMID 41047873, 2025). "HGBL includes two types: high-grade B-cell lymphoma, accompanied by MYC and Bcl-2 and/or Bcl-6 rearrangement (HGBLR), and high-grade B-cell lymphoma, not otherwise specified (HGBL, NOS), this type has a low incidence and is clinically rare." (PMID 36618391, 2022). "Immunostaining revealed that Methylated person C and E cells were positive for CD20, CD10, and BCL‐6 and negative for MUM‐1, indicating that both of these cells were GCB in B‐cell lymphoma." (PMID 36618443, 2021). "High-grade B-cell lymphoma, NOS includes blastoid-appearing large B-cell lymphomas and cases lacking MYC and BCL2 or BCL6 translocations." (PMID 31484540, 2019). "High grade B-cell lymphomas include the entities carrying MYC, BCL2 and/or BCL6 translocations or cases with blastoid morphology without DH translocations." (PMID 31942539, 2019). "However, specific immunohistochemical markers for B-cell lymphoma, including CD5, CD10, CD23, BCL6, CyclinD-1, and CD38, which are typically negative." (PMID 39834941, 2024). "However, the 2022 World Health Organization (WHO) and International Consensus Classification (ICC) recommendations re-categorized MYC/BCL6 as “DLBCL, not otherwise specified” and MYC/BCL2 and MYC/BLC2/BCL6 as “DLBCL/high-grade B-cell lymphoma-MYC/BCL2”." (PMID 39696503, 2024). "In these studies, the histology-related inclusion criteria were different; in general, the studies included high-grade B-cell lymphoma (HGBCL) with or without translocations of MYC and BCL2 and/or BCL6 (double/triple-hit lymphoma) and transformed follicular lymphoma (tFL)." (PMID 36561713, 2022). "In conclusion, the results of our study confirm that R-CHOP is not an appropriate therapeutic choice for “high-grade B-cell lymphoma with MYC and BCL2/BCL6 rearrangements”, and that intensive regimens or DA-EPOCH-R should be preferred, especially for younger patients." (PMID 31976479, 2019). "Moreover, the cells were found to be positive for CD20, BCL-2, BCL-6 and IRF-4 (Mum-1) and be negative for CD10 and CD5 by Immunofluorescence, which was similar to the immunophenotypic profiles of the majority of HBsAg-positive B-cell NHL patients." (PMID 31120924, 2019). "Furthermore, although Bcl-6 is also expressed in Burkitt lymphoma, its role has not been investigated, yet it is expressed in all cases and is likely to contribute to proliferation and survival, since the BCL6 gene has long been recognized as an important oncogene in B-cell lymphoma." (PMID 33412518, 2021).
diffuse large B-cell lymphoma (209 papers, 2006 to 2026). "In this study, we focus on diverse translocations that share a common partner, BCL6 on chromosome 3, which are implicated in diffuse large B-cell lymphoma (DLBCL)." (PMID 41812881, 2026). "This discovery opens up new possibilities for developing anticancer drugs targeting BCL6-associated cancers, such as diffuse large B-cell lymphoma." (PMID 40027134, 2025). "For instance, BCL6 (encoded by Bcl6), a key transcription factor essential for GC B cell differentiation, was noticed because of its mutations in GC B cell-derived diffuse large B cell lymphoma." (PMID 32587588, 2020). "Further, BCL6 has been implicated as an oncogene primarily in B-cell malignancies such as diffuse large B-cell lymphoma (DLBCL)." (PMID 32234966, 2020). "FBXO11 has been found to be mutated in multiple diffuse large B-cell lymphoma cell lines and this inactivation correlates with increased levels and stability of BCL6." (PMID 26471094, 2015). "On the other hand, mutations and chromosomal translocations leading to Bcl6 over-expression is associated with about 40% of diffuse large B cell lymphomas." (PMID 24892698, 2014). "The identified association among FOXP1, BCL2, and BCL6 indicates the possibilities of uncovering the development process in diffuse large B-cell lymphoma tumor cells." (PMID 23289441, 2013). "However, constitutive expression of BCL6 by chromosomal translocations or aberrant somatic mutations causes diffuse large B cell lymphoma." (PMID 36377663, 2022). "High‐grade B‐cell lymphoma with MYC and BCL2 and/or BCL6 rearrangements (HGBL‐DH/TH) comprise ∼8% of tumors with diffuse large B‐cell lymphoma (DLBCL) morphology and is associated with poor outcome after standard R‐CHOP (rituximab, cyclophosphamide, doxorubicin, vincristine, and prednisone) therapy." (PMID 35846101, 2021). "More importantly, this proinflammatory action of Bcl6 appeared to be relevant to a well-known clinic entity, diffuse large B-cell lymphoma associated with chronic inflammation (DLBCL-CI), which was characterized by high Bcl6 level and simultaneously sustained inflammation." (PMID 26728228, 2016). "Bcl-6 is closely associated with the occurrence and development of diffuse large B-cell lymphoma (DLBCL) and follicular lymphoma (FL); 20%–40% of DLBCL and 15% of FL patients have the Bcl-6 3q27 chromosome translocation." (PMID 28410239, 2017). "Also, since BCL6 interacts with several co-repressor complexes to inhibit transcription, and its gene is frequently trans-located and hyper-mutated in diffuse large B cell lymphoma (DLBCL), miR-155 acts to enhance transcription and contribute to the pathogenesis of DLBCL." (PMID 24073882, 2013). "BCL6 plays significant roles in various cellular processes and malignancies such as diffuse large B-cell lymphoma." (PMID 41726161, 2026). "In diffuse large B cell lymphoma, BCL6 suppresses cell death genes, hence promoting tumor growth, while this progression can be eliminated by inhibiting BCL6102." (PMID 40607252, 2025). "In sporadic Burkitt lymphoma, erroneous AID-mediated class-switch recombination (CSR) drives immunoglobulin locus (Ig)-MYC translocations, while diffuse large B-cell lymphomas (DLBCLs) commonly harbor Ig-BCL6 translocations through similar mechanisms." (PMID 40270606, 2025). "This inhibitor was shown to specifically kill BCL6-positive diffuse large B cell Lymphoma (DLBCL) cell lines." (PMID 41246349, 2025). "B-cell lymphoma 6 (BCL6) is a proto-oncogene located on chromosome 3q27, also known as zinc finger and BTB domain containing 27 (ZBTB27), which was first identified in diffuse large B-cell lymphoma." (PMID 40821118, 2025). "Previous research in diffuse large B‐cell lymphoma has shown that MEF2B directly activates the transcription of BCL6 in germinal center (GC) B cells." (PMID 39931830, 2025).
diffuse large B-cell lymphoma (continued). "In our previous work, we successfully identified a series of N-phenyl-4-pyrimidinamine BCL6 inhibitory activities against diffuse large B-cell lymphoma in vitro and in vivo." (PMID 40821118, 2025). "In summary, we provided the first evidence that loss of E3 ubiquitin ligase FBW7 in VE-cadherin positive endothelial cells instigates diffuse large B-cell lymphoma via upregulation of BCL6 stability." (PMID 38485719, 2024). "We conclude that selective deletion of E3 ubiquitin ligase FBW7 in VE-cadherin positive endothelial cells instigates diffuse large B-cell lymphoma via upregulation of BCL6 stability." (PMID 38485719, 2024). "It targets oncogenic proteins, such as BCL-6 or the Snail family of transcription factors, for degradation, thereby exhibiting a tumor-suppressive function in various cancer types, such as diffuse large B-cell lymphomas and lung cancer." (PMID 39137238, 2024). "Knockout of AIP resulted in decreased BCL6 expression and reduced cell viability of a diffuse large B cell lymphoma (DLBCL) cell line." (PMID 38479600, 2024). "miR-10a suppresses cell proliferation and promotes apoptosis by targeting BCL6 in diffuse large B-cell lymphoma." (PMID 39769169, 2024). "CD10 and BCL6 are typically labeled follicular center cell-associated antigens more commonly associated with other NHL types such as follicular lymphoma, diffuse large B-cell lymphoma (DLBCL), and Burkitt lymphomas." (PMID 37373354, 2023). "In particular, in cases expressing both CD10 and BCL6, the differential diagnosis with follicular lymphoma or GC-B-diffuse large B-cell lymphoma should be raised, and molecular techniques must support the diagnosis." (PMID 37835560, 2023). "In diffuse large B cell lymphoma, the SE at the BCL6 locus similarly serves as an “enhancer donor” in translocations to activate distal oncogenes, such as MYC." (PMID 37415185, 2023). "B-cell lymphoma 6(BCL6) is a transcriptional repressor and oncogenicdriver of diffuse large B-cell lymphoma (DLBCL)." (PMID 37026591, 2023). "BCL6 overexpression drives the pathobiology of many B cell malignancies, including diffuse large B cell lymphoma (DLBCL)." (PMID 36483537, 2022). "Damaging mutations in primary cutaneous diffuse large B-cell lymphoma of the leg type, involving MYD88 gene, or BCL6 and MYC translocations or CDKN2A deletions are useful for diagnostic purposes." (PMID 36291756, 2022). "BCL6 was discovered as a gene involved in reciprocal chromosomal translocations, often with the immunoglobulin heavy chain locus, in about 25% of diffuse large B-cell lymphoma (DLBCL)." (PMID 34274316, 2021). "Fusions involving the immunoglobulin (IG) loci and one of BCL2, BCL6, or MYC are hallmark aberrations of diffuse large B-cell lymphoma and are hard to detect owing to the poor mappability of the IG loci." (PMID 33441414, 2021). "The transcription factor BCL6 is a known oncogenic driver of lymphoid malignancies such as diffuse large B cell lymphoma (DLBCL)." (PMID 33795634, 2021). "Downregulation of CKIs by BCL6 protein is frequently reported in lymphocytes, normal germinal center B and diffuse large B cell lymphomas-derived cells." (PMID 31903146, 2020). "We performed FISH analyses for c-Myc, BCL2 and BCL6 genes to subclassify diffuse large B-cell lymphoma on cases received after the 2017 WHO edition." (PMID 32992679, 2020). "Upregulated levels of hsa-miR-127-3p are reported in testicular and nodal diffused large B-cell lymphoma, with an inverse correlation to BCL6 levels." (PMID 32849505, 2020). "In this study romidepsin, a potent histone deacetylase inhibitor (HDACi), induced apoptosis and cell cycle arrest in Burkitt and diffuse large B-cell lymphoma cell lines, which are model cells for studying the mechanism of action of BCL6." (PMID 31712669, 2019). "Our findings describe AIP as a positive regulator of BCL6 expression with implications for the pathobiology of diffuse large B cell lymphoma." (PMID 31042473, 2019).